RAG2 (recombination activating 2)
Diseases named in the same sentence as RAG2 in open-access papers (continued):
Sharing a sentence is not in itself a finding about the gene and the disease.
tumor (continued). "To validate these findings in vivo, we administered anti-TIGIT mAb to A20 tumor-bearing Rag2-/- mice following the experimental scheme." (PMID 40231264, 2025). "In vivo tumor growth assay in Rag2/γc mice showed apelin-increased growth, while apelin-dm significantly reduced it." (PMID 39962271, 2025). "To verify the anti-tumor role of NK cells in Rag2-/- mice, we performed FACS analysis to examine infiltration of the interferon gamma (IFNγ) producing NK cells in tumors treated with vehicle and indisulam for 3 days, respectively." (PMID 40962798, 2025). "Treatment with 5-AZA and its combination with a COX2i led to strong repolarization of the immune TME, increasing inflammatory monocytes and T cell infiltration that in turn led to tumour regression in all Rag2–/– mice receiving ACT." (PMID 39604727, 2025). "Following confirmation of the formation of a HN in the F344 Il2rg Rag2 double KO rat model, an orthotopic OS tumour was induced within the HN of the eight remaining rats." (PMID 41315643, 2025). "To evaluate the functional implication of Nrn1-/- Treg suppression in disease settings, we challenged the Rag2-/- hosts with the poorly immunogenic B16F10 tumor." (PMID 39565188, 2024). "Most tumor cells in STAT5 GOF Rag2–/– mice are DP or SP8, suggesting progression in thymic development beyond the DN stage, despite TCR deficiency due to loss of VDJ rearrangement." (PMID 38618957, 2024). "We examine the effects of ASNS deletion on tumor growth and the subsequent rewiring of metabolic pathways in male and female Rag2/IL2RG mice." (PMID 38886847, 2024). "Transgenic expression of mylpfa:myf5, a transgene that drives myf5 expression in terminally differentiated, myosin light chain 11 (mylpfa) expressing cells, resulted in higher penetrance of rag2-kRASG12D tumor formation." (PMID 39902277, 2024). "(F) her4.1:mScarlet and rag2:EGFP expression in live zebrafish with a p53EPS tumor at 30 days post fertilization (dpf)." (PMID 39052000, 2024). "To confirm that the initial control observed against KPAdpgk tumor cells was mediated by an adaptive immune response, we implanted all cell lines into Rag2-/- mice and observed that all three cell lines grew progressively with similar kinetics." (PMID 37548358, 2023). "Comparison of zebrafish prkdc, rag2 and jak3 mutant models has revealed the prkdc mutants as the most efficient platform for tumor xenotransplantation." (PMID 37047441, 2023). "(A) Tumor growth of KP-HetHigh tumor cells was implanted subcutaneously (s.c.)into Batf3-/-, Rag2-/- and WT mice." (PMID 37548358, 2023). "The similarity in response to combined inhibitor treatment in RAG-1-/- and RAG-2-/- γc-/- mice suggests that NK cells contribute little to the anti-tumour activity of the treatment." (PMID 37582853, 2023). "Most human tumors are established in immunodeficient recipient mice (nude/rag2/scid) to prevent xenograft rejection, but this approach lacks an adaptive immune system, limiting its relevance for studying anti-tumor treatment." (PMID 37961626, 2023). "(E) Schematic and tumor growth of KPAatf and KPAdpgk in Rag2-/- mice after adoptive T cell transfer (ACT) from naïve or tumor-bearing mice on day 4 after tumor injection." (PMID 37548358, 2023). "To improve the homogeneity, antigen‐specificity and reduce possible autoreactivity, here we developed a technique to generate antigen‐specific T cells from Rag2 gene‐deleted pluripotent stem cells (PSCs) and further measured their anti‐tumour efficacy." (PMID 36592612, 2023). "A total of 23 surgically removed tumor tissues from 14 male and 7 female patients aged between 43 and 83 were engrafted in Rag2/SCID mice at 1 × 105 viable cells per mouse." (PMID 37415222, 2023). "The control of KP-HetLow tumors was completely lost in Rag2-/- mice, indicating that tumor control was mediated by an adaptive immune response." (PMID 37548358, 2023).
tumor (continued). "We found that tumor volumes and weights were increased in Rag2-/- mice that were administered Aurkafl/fl platelets and in mice that were administered Aurkafl/fl;Cd19cre/+ platelets." (PMID 37064877, 2023). "Our attempts to generate a resistance model using the Rag2 KO mouse strain were unsuccessful, despite various attempts to optimize tumor growth induction by adjusting tumor cell number, cell lines and/or the addition of Matrigel." (PMID 38239393, 2023). "The results of this study demonstrated good reproducibility and the establishment of a recurrent, drug-resistant, patient-derived GBM10 tumor in the recently developed Rag2-null rat." (PMID 36483050, 2022). "MOLM-13 cells expressing either CSF2RB shRNA or control shRNA were injected subcutaneously into the flanks of Rag2/Il2rg-mutant mice and tumor growth was monitored by caliper measurements." (PMID 34750506, 2022). "We tested the ability of trametinib to stop tumour growth, using A375 cells injected s.c. in the flank of adult female 8HUM_Rag2-/- mice." (PMID 37065929, 2022). "Nevertheless, the high GBM10 implantation success rate in our Rag2-null rat cohort is promising, and the tumor growth characteristics were relatively consistent across all rats studied." (PMID 36483050, 2022). "All together, these data show that adult rag2−/−X. tropicalis animals allow stable allografting of transplanted GEXM-derived tumor cells in different cancer contexts." (PMID 36230482, 2022). "In another preliminary unpublished study from our lab, four of four (100%) Rag2-null rats were permissive to intracranial U87 tumor growth." (PMID 36483050, 2022). "To examine the role of the adaptive immune system in stress increased tumor development, we exposed recombination‐activating gene 2 (Rag2)−/− mice to AR." (PMID 35224894, 2022). "At this point tumours in the 8HUM_Rag2-/- mice had regressed to the point where they were essentially undetectable, and trametinib treatment was stopped." (PMID 37065929, 2022). "For example, rag2 knockout zebrafish have been used to visualize tumor neovascularization while prkdc knockouts have supported long-term engraftment of xenotransplanted gastrointestinal cancer cells." (PMID 35216498, 2022). "Initial studies have focused on refining the imaging and targeting healthy organs with histotripsy in preparation for planned tumor ablation studies in the RAG2/IL2RG knockout orthotopic pig model." (PMID 34478363, 2022). "A marked decrease in UPS tumor volume was observed in DMXAA treated Rag2 KO mice (days 7-14), with tumor volumes sharply rebounding afterwards." (PMID 36700206, 2022). "The antitumor response of NMD inhibition was dependent on the immune system, as tumor kinetics of 4T1 SMG1KD was similar to the control when implanted in immunodeficient mice (Rag2/IL2rg-/-)." (PMID 36443756, 2022). "In summary, we document the generation of a rag2 mutant Xenopus tropicalis line that allows the stable engraftment of tumor cells." (PMID 36230482, 2022). "Tumor models were established by subcutaneous injection of tumor cells in Bl6/Rag2/GammaC double knockout mice." (PMID 34659556, 2021). "Lastly, to evaluate the influence of CREG1 on tumor progression in vivo, shCreg1 PyMT cells were orthotopically transplanted into the mammary fat pad of Rag2−/− γc−/− immunosuppressed mice." (PMID 32385587, 2021). "Compared to immunologically competent C57Bl/6 mice, tumours transplanted in Rag2 KO mice displayed similar tumour growth kinetics and survival time." (PMID 34242269, 2021). "To validate our initial in vitro CRISPR/Cas9 screen we exposed IFNγR2- and Jak1-mutant tumor cells to activated 2 C/Rag2–/– T cells to evaluate lysis." (PMID 32001684, 2020).
tumor (continued). "In vitro-primed CD8+ T cells isolated from 2 C/Rag2–/– TCR transgenic mice were co-cultured with transduced B16.SIY tumor cells." (PMID 32001684, 2020). "RAG2-/-, γc-/- or NSG mice (deficient in T, B and NK cells but maintain functional phagocytes) were used for tumor engraftment." (PMID 33603751, 2020). "To determine if the spontaneous tumor control was dependent upon adaptive immunity, we inoculated Rag2–/– mice with WT, IFNγR2-, or Jak1-mutant tumor cells and tracked tumor growth." (PMID 32001684, 2020). "Rag2/IL2rg-/- double knockout impelled SCID in mice; next, we attempted to transplant various human-tissue-derived primary and passage tumor cells into these mutated mice." (PMID 31134127, 2019). "We found that LTX-315 controlled tumor burden equally during the first four days in both mouse cohorts, whereas a control group confirmed tumor growth in un-treated Rag2–/– mice." (PMID 31799501, 2019). "Taken together, our findings suggest Rag2/IL2rg-/- double-knockout mice represent an ideal xenograft tumor model, as this mouse type showed compromised growth of various tissue-derived cancer cells and different inoculation methods." (PMID 31134127, 2019). "Surprisingly, while tumor growth reduction was slightly less efficient, the HSD effect was still detectable in RAG2 deficient mice, indicating that T cells rather play a minor role in this model." (PMID 31214164, 2019). "Consistent with a T cell phenotype, qPCR from purified tumor cells showed high cd3 mRNA expression at levels comparable to those in Tg(rag2:Myc) transgenic tumors and normal thymocytes." (PMID 29941549, 2018). "When tumor cells harvested from Tg(rag2:jdp2) fish were injected into the circulation of 2-d-old rag2E450fs (Casper) mutant embryos, they rapidly migrated to and engrafted in the thymus of recipient larvae, consistent with their thymic origin." (PMID 29941549, 2018). "QBKPN administration reduced tumor burden in RAG2 knockout mice, and this response was comparable to immune-intact mice." (PMID 29399400, 2018). "We thus coinjected single-cell embryos with rag2:mCherry, rag2:mCherry/rag2:Myc, or rag2:mCherry/rag2:Myc/rag2:jdp2 and monitored the fish by fluorescent microscopy for tumor onset." (PMID 29941549, 2018). "A subsequent experiment on the Rag2-KO background showed that treatment of NKG2D-WT mice with anti-NKG2D antibody in vivo starting the day before tumor cell implantation resulted in enhanced control of B16 tumors comparable to the NKG2D-KO mice." (PMID 29231815, 2017). "Of note, the neoplasia score was significantly higher (p < 0.01) in MDR1A/RAG2 dKO tumors compared to MDR1A KO tumors." (PMID 28686677, 2017). "Tumour fragments from 147 unsupervised, surgical prostate samples were implanted subcutaneously into immunodeficient Rag2-/-γC-/- mice within 24 hours of surgery." (PMID 29145505, 2017). "Although the average number of tumors that developed per mouse was generally decreased in RAG2-deficient strains, compared to WT or MDR1A KO mice, the remaining MDR1A/RAG2 dKO mice showed a higher tumor burden than RAG2 KO." (PMID 28686677, 2017). "Primary tumour fragments, from 147 patients, were implanted subcutaneously into Rag2-/-γC-/- mice resulting in tumour outgrowths from 47 biopsies (32% primary outgrowth rate)." (PMID 29145505, 2017). "In a subset of cases patient derived xenografts (PDX) were obtained upon tumor cell inoculation in rag2/IL2 knock-out mice." (PMID 26928703, 2016). "We analysed the thymi of both CD4NA/RAG+/+ and CD4NA/RAG2−/− mice before the presentation of overt tumours." (PMID 26753883, 2016).
tumor (continued). "Here, we studied VGSC expression in tumours following orthotopic implantation of luciferase-expressing MDA-MB-231 cells into the mammary fat pad of female Rag2-/-Il2rg-/- mice, a robust model of BCa growth and metastasis." (PMID 25623198, 2015). "The tumor weight range of the rag2 mice varied between 0.08 g and 2.61 g (mean 1.16 g) whereas in the pfp/rag2 mice the weight range varied between 0.20 g and 2.74 g (mean 1.23 g)." (PMID 25373310, 2014). "Lung metastases in pfp/rag2 mice consisted of 10–100 tumor cells while those in rag2 mice were generally disseminated tumor cells (DTCs)." (PMID 25373310, 2014). "In order to study the influence of perforin-dependent direct cytotoxicity of NK cells on primary tumor growth and the number of metastatic deposits formed, we used two different mouse strains, namely rag2 and pfp/rag2 mice on the same genetic background." (PMID 25373310, 2014). "This is in line with the data generated by a computer modelling of cancer spread which revealed that 80% of the circulating tumor cells in the blood of rag2 mice had been eliminated by NK cells before extravasation was possible." (PMID 25373310, 2014). "In rag2 mice 2,9% of the tumor cells were mitotic compared to 3.9% of the tumor cells in pfp/rag2 mice." (PMID 25373310, 2014). "Circulating tumor cells (CTC) in murine blood were nearly three times higher in pfp/rag2 (68 cells/ml) than in rag2 mice (24 cells/ml)." (PMID 25373310, 2014). "Since the same cell type was used in both mouse types, the primary tumor should exhibit the same spreading behavior in the pfp/rag2 and the rag2 mouse stain." (PMID 25373310, 2014). "Typical metastasis detected in rag2 mice consisted of only 1–10 cells at the maximum whereas disseminated tumor cells (DTC) were the most common presentation of metastasis in the rag2 mice." (PMID 25373310, 2014). "During tissue immunofluorescence analysis we serendipitously detected intra-ovarian and peritoneal metastases in an Ad5ROBO4 injected (1.5×1011 vp) hCAR:Rag2−/− mouse bearing an orthotopic tumor." (PMID 24376772, 2013). "For this purpose, we co-transfered B16 tumor cells with NK cells isolated from wild type and nAChR β2−/− mice, into the recipient RAG2−/−γc−/− mice." (PMID 23469004, 2013). "We first compared TSGs derived from the same parent tumor, HRPCa-1, but maintained in two mouse strains, RAG2−/−γc−/− and NIH III; both lack T, B, and natural killer cells but the extent of the deficiencies in each has not been established." (PMID 23985008, 2013). "Injection of a rag2-hKRASG12D construct drives tumor formation; additional genes on separate, linearized plasmids are also driven by rag2 and co-integrate with and are co-expressed in the rag2-hKRASG12D tumors." (PMID 23705022, 2013). "Clearly, the lungs of RAG2−/−γc−/− mice had larger tumor burden and majority of these mice quickly succumb to death after B16 cell challenge." (PMID 23469004, 2013). "Phenotypic analysis was carried out using flow cytometry on the tumor cells that grew in Rag2-/- mice." (PMID 21269511, 2011). "Disaggregated primary tumor cells that were injected intra-femorally (IF) generated tumors in all eight Rag2-/-;γc-/- mice." (PMID 22035283, 2011). "Similar to TM40D, all of the RAG2 KO mice implanted with TM40D-MB tumor cells readily metastasized to lung, and the overall number of lung metastases for both groups were significantly greater than in wildtype mice (P<0.001)." (PMID 21695190, 2011). "Tumor development was assessed in these animals and the tumor bearing Rag2-/-mice were sacrificed at various time points after the injection." (PMID 21269511, 2011). "Minced tumor sample that was injected sub-cutaneously (SQ) produced xenograft tumors in all ten male Rag2-/-;γc-/- mice." (PMID 22035283, 2011). "Here we show that these GFAP-luc; Rag2-/- mice injected with malignant glioma cells can be used to monitor and quantify tumor-induced astrogliosis response of the host." (PMID 21247490, 2011).
tumor (continued). "In vivo, reconstituted Rag2−/−/γc−/− mice had higher survival rates after K562 challenge compared to non-reconstituted Rag2−/−/γc−/− mice and were able to control tumor burden in various organs." (PMID 20027308, 2009). "The mechanism of cytokine-mediated tumour cell rejection was assessed in tumourigenicity studies performed in γc/RAG2 knockout mice, which lack any T, B, or NK cells." (PMID 12771934, 2003). "In the literature, only 1 case of CNS vasculitis with partial RAG2 deficiency has been described but did not present with imaging findings mimicking tumor as in our case." (PMID 41503114, 2026). "Accordingly, CD45−CD31high tumor endothelial cells and TA-HECs were not modulated in lymphocyte-deficient Rag2−/− mice after treatment with 9H10." (PMID 40460830, 2025). "To test whether re-establishment of a functional IFN-I pathway in RTT cancer cells is sufficient to restore responses to ACT, we overexpressed IRF3/7 in RTT cells and established tumours in Rag2–/– mice." (PMID 39604727, 2025). "Notably, the anti-tumor effects of KYNA are abrogated in T cell-deficient mouse models (nude and Rag2-/-), confirming its dependence on adaptive immunity." (PMID 41221633, 2025). "To determine whether Ogt deficiency is dependent upon adaptive immune system, we inoculated MC38 control and Ogt knockout cells into immunodeficient Rag2–/– mice and tracked tumor growth." (PMID 38168435, 2024). "In a RAG2-deficient model with and without T cell reconstitution, we show that T cells are required for calcium flashing in tumour cells." (PMID 37258670, 2023). "On Day 18 after B16F10‐OVA injection, the tumour sizes of Rag2−/−‐OT1‐iT‐treated mice were less than 100 mm2, but those of PBS‐treated tumour‐bearing mice were over 200 mm2 (n = 5, p < 0.001), indicating that Rag2−/−‐OT1‐iT cell therapy inhibits tumour growth significantly." (PMID 36592612, 2023). "This more robust immune activity could have triggered an amplified immune response against the implanted tumor cells, ultimately inhibiting their growth and engraftment in the Rag2 KO mouse strain." (PMID 38239393, 2023). "Besides, they transplanted adoptive T cells from radiated mice to Rag2 KO (immunocompromised) mice, the tumor tissues of Rag2 KO mice achieved sustained complete response, suggesting the tumor suppression was dependent on T-cells activation." (PMID 36632233, 2023). "To see if Rag2−/−‐OT1‐iT cells could efficiently kill tumour cells in vitro, we assessed their capacity to eradicate E.G7‐OVA tumour cells according to the prior research." (PMID 36592612, 2023). "(C, D) Mice were injected s.c. with 1 × 106 tumor cells in (B) WT mice or (C) Rag2-/- mice." (PMID 37548358, 2023). "(B) Tumor growth of KP-HetHigh and KP-HetLow in WT and Rag2-/- mice." (PMID 37548358, 2023). "This phenotype was recapitulated in LK-2 tumors that developed in Rag2–/–Il2rg–/–Cd47–/– recipient mice, where a significantly higher proportion of parental LK-2 than CALB1-deficient LK-2 2B7 tumor cells stained positive for p63, a marker for squamous epithelial differentiation encoded by TP63." (PMID 37192000, 2023). "To functionally determine if the tumor regression phenotype was mediated by adaptive antitumor immunity, we implanted IRE1αWT or IRE1αKO cancer cells into wildtype or Rag2-deficient hosts lacking T and B cells." (PMID 36624093, 2023). "Efficient tumor cell transplantation might also be achieved via alternative techniques apart from the generation of the rag2−/− line." (PMID 36230482, 2022). "This study aimed to develop a recurrent, drug-resistant patient-derived tumor model (GBM10) using the novel Rag2-null rat and to determine whether the tumor maintains the histologic/pathologic features of GBM in humans." (PMID 36483050, 2022). "Thus, we implanted 1 × 106 INA-6 iRFP-labelled IL-32 KO and WT cells into humanized bone scaffolds in immune compromised female RAG2−/− GC−/−mice and followed tumor growth by imaging." (PMID 35005550, 2022).